RNU6-579P (RNA, U6 small nuclear 579, pseudogene)
Gene: Small nuclear RNA gene on chromosome 2 (133,333,829 to 133,333,930, forward strand). Ensembl gene ENSG00000252688.
Homologues: Orthologues: macaque U6 (92% identical), chimpanzee U6 (88% identical), guinea pig U6 (65% identical). Paralogues in human: RNU6-939P (76% identical), RNU6-1075P (75% identical), RNU6-704P (75% identical), RNU6-536P (74% identical), RNU6-767P (74% identical), RNU6-1020P (73% identical), RNU6-1060P (73% identical), RNU6-1175P (73% identical), RNU6-11P (73% identical), RNU6-141P (73% identical), RNU6-16P (73% identical), RNU6-183P (73% identical), and 1284 more.